Y_RNA (Y RNA )
Gene: Miscellaneous RNA gene on chromosome 17 (61,874,084 to 61,874,182, reverse strand). Ensembl gene ENSG00000202361.
Homologues: Orthologues: chimpanzee Y_RNA (100% identical), macaque Y_RNA (96% identical). Paralogues in human: Y_RNA (86% identical), Y_RNA (85% identical), RNY3 (84% identical), Y_RNA (84% identical), RNY3P1 (83% identical), Y_RNA (83% identical), Y_RNA (82% identical), RNY3P16 (81% identical), Y_RNA (81% identical), RNY3P14 (80% identical), Y_RNA (80% identical), RNY3P4 (79% identical), and 93 more.